CRP (C-reactive protein)
Diseases named in the same sentence as CRP in open-access papers (continued):
Sharing a sentence is not in itself a finding about the gene and the disease.
autoimmune disease (continued). "The distribution of MMR status also served as a measurement of internal validity, since it is unlikely that other reasons for elevated CRP, such as autoimmune disease or infection, were missed when scrutinizing the records since all cases with the highest CRP had the same MMR status (pMMR)." (PMID 32316975, 2020). "Omega-3 fatty acids present with anti-inflammatory and immunomodulatory effects and might be potential therapeutic agents for inflammatory and autoimmune diseases through decreasing the levels of C-reactive protein, IL-6, and TNF-α." (PMID 32423112, 2020). "Similarly, modest CRP-responses are recorded in autoimmune diseases characterized by increased type I interferon (IFN) activity, e.g., SLE, and lack of correlation between IL-6 and CRP has been demonstrated in patients with SLE." (PMID 33584722, 2020). "Thus it can be seen that Cyr61may mediate neutrophil infiltration and CRP product in advanced ovarian serous adenocarcinoma just like it acts in the inflammation or autoimmune diseases." (PMID 31766991, 2019). "Samples were then stratified into 4 sub-groups according to diagnosis at admission to hospital: infectious diseases (n = 42), cancer (n = 16), heart or brain ischemia (n = 10), and others (trauma, autoimmune diseases) (n = 19), and CRP-sP2X7R correlation in the 4 diagnosis sub-groups analyzed." (PMID 31031771, 2019). "Second, an elevated CRP level may reflect a state of concurrent autoimmune diseases or chronic inflammatory disease during the study enrolment." (PMID 30718369, 2019). "C-reactive protein (CRP) is one of acute phase proteins, the serum or plasma levels of which rise during general non-specific response to a wide variety of diseases, either infectious or inflammatory including autoimmune diseases." (PMID 29780224, 2018). "Analyses were adjusted for age, sex, smoking status, cumulative smoking, alcohol intake, body mass index, plasma C-reactive protein, blood neutrophil count, recent infection, Charlson comorbidity index, autoimmune diseases, medication use, and immunodeficiency/hematologic disease." (PMID 30383787, 2018). "Thus, we conducted this study to investigate the role of PCT and sTREM-1 along with CRP in differentiating infection from disease flare prospectively in febrile patients with autoimmune diseases." (PMID 27096761, 2016). "However, CRP is strongly affected by other diseases, such as infection, cardiovascular disease, and autoimmune disease." (PMID 25612215, 2015). "In fact, low HDL-C in autoimmune diseases including RA often negatively correlated with acute phase reactants including CRP and erythrocyte sedimentation rate, and further results also showed that these acute phase reactants are at least partially responsible for the presence of low HDL-C in RA." (PMID 24587064, 2014). "Moreover, several authors have suggested a link between childhood trauma and a possible increase in proinflammatory cytokines, such as interleukin 6 (IL-6), TNF-α, and C-reactive protein (CRP), which are known to be associated with autoimmune diseases and chronic inflammatory diseases." (PMID 40837576, 2025). "These discrepancies might be explained by the fact that CRP tests assess relatively higher levels of inflammation (typical for conditions like infections, autoimmune diseases, or trauma), while Hs-CRP is much more sensitive and can detect very low levels of inflammation." (PMID 40529359, 2025). "Including variables like disease duration, other relevant biomarkers (e.g., C-reactive protein, erythrocyte sedimentation rate), and patient-reported outcomes would allow the model to capture a more comprehensive picture of the factors influencing treatment response in autoimmune diseases." (PMID 40027855, 2025).
autoimmune disease (continued). "While direct evidence for the impact of MLLT10 on autoimmune diseases has not been established, studies indicated a close association with C-reactive protein levels, widely recognized as a valuable indicator of disease activity in various autoimmune rheumatic diseases." (PMID 38616254, 2024). "Additionally, while we excluded patients with active infections or autoimmune diseases, the specific causes of elevated CRP levels were not identified." (PMID 38104105, 2023). "Low doses of CRP could modulate autoimmune diseases and prevent the generation of autoantibodies." (PMID 32168865, 2020). "Interestingly, it has been reported that patients with autoimmune diseases, compared to healthy subjects, have a reduced synthesis of GCs and altered CRP and cortisol/CRP ratio, in response to chronic inflammations such as polymyalgia rheumatica and giant cell arteritis." (PMID 30662460, 2018). "Interestingly, SAA antigen serum levels do not correlate to their respective anti-SAA or anti-SAA1α autoantibodies, similarly to our previous study on a smaller number of HBDs, as well as a report on CRP and anti-CRP autoantibodies in a population of connective tissue and autoimmune diseases." (PMID 29617422, 2018). "Thus, ESR or CRP may be used as indices of disease severity, but care must be taken to identify coincident inflammatory insults such as infection or autoimmune disease." (PMID 25408853, 2014). "Although the specific pathways remains unclear, a number of inflammatory and immune mediators seem to have a role, including C-reactive protein (CRP), cytokines, chemokines and growth factors, most of them dysregulated in RA patients and implicated in the pathogenesis of autoimmune diseases." (PMID 24465874, 2014). "C-reactive protein (CRP) is an acute phase reactant which is elevated in multiple medical conditions, including infection, malignancy, and autoimmune disease." (PMID 40007616, 2025). "The incidence rate of CRP ≥ 8 mg/L was significantly higher when neonates exposed to PROM(≥ 18 h), maternal autoimmune diseases and MAS; and significantly lower when newborns exposed to antenatal steroids, placenta previa, ICP and cesarean delivery." (PMID 38302903, 2024). "IL-6, along with C-reactive protein (CRP), is commonly used as a serum biomarker to monitor inflammation in patients with cancer, infection, or autoimmune diseases due to its crucial role in activating and sustaining the inflammatory response." (PMID 37760027, 2023). "Serum CRP level is used as a biomarker in inflammatory conditions such as IBD and autoimmune disease but remains understudied in the realm of IMDC." (PMID 37476185, 2023). "However, CRP is not a specific marker; many causes could increase CRP levels, such as autoimmune disease, cancer surgery, and trauma." (PMID 36443747, 2022). "Many chronic diseases, such as cardiovascular diseases, cancer, and autoimmune diseases, are related to increased levels of inflammatory factors such as IL-1β, IL-6, tumor necrosis factor (TNF), and C-reactive protein (CPR)." (PMID 36062133, 2022). "The results showed that serum HMGB1 concentration moderately correlated with CRP concentration in infectious subgroup, while serum anti-HMGB1 antibodies were strongly correlated with ESR in autoimmune disease subgroup." (PMID 33658546, 2021). "In this study, we assessed the correlation of serum HMGB1 and anti-HMGB1 antibodies concentrations with disease activity indicators (CRP and ESR) in FUO infectious disease subgroups and autoimmune disease subgroups using the bivariate correlation analysis." (PMID 33658546, 2021). "Abnormal expression of IL13 is found in many autoimmune diseases with an inflammatory response, while IL6 is released mainly by white blood cells and activates the synthesis of acute phase proteins, like CRP." (PMID 31194785, 2019).
autoimmune disease (continued). "A positive correlation was found between levels of CRP and PCT, and cut-off values of CRP and PCT for differentiating bacterial infection from disease flare are higher than those of other autoimmune diseases." (PMID 31777354, 2019). "The effect of marine-derived n-3 PUFAs from dietary intake on CRP, IL-6 and TNF-α was only assessed in subjects with chronic non-autoimmune disease, and significant lowering effect was only observed on IL-6, but not on CRP and TNF-α." (PMID 24505395, 2014). "In the current study, CSF WBC and protein, serum CRP and IgG were higher in NMOSD patients with autoimmune diseases." (PMID 25135481, 2014). "The present meta-analysis provided consistent evidence that marine-derived n-3 PUFAs supplementation had a significant lowering effect on fasting blood levels of CRP, IL-6 and TNF-α in subjects with chronic non-autoimmune disease and healthy subjects." (PMID 24505395, 2014). "Restricted cubic spline analysis and subgroup analysis showed that the lowering effect of marine-derived n-3 PUFAs on CRP, IL-6 and TNF-α in subjects with chronic non-autoimmune disease became weakened when body mass index was greater than 30 kg/m2." (PMID 24505395, 2014). "C-reactive protein (CRP) is an acute-phase reactant to microbial infection, trauma, infarction, autoimmune diseases or malignancies." (PMID 24148787, 2013). "Nevertheless, cardiac MRI findings in patients with autoimmune disease tend to be independent of CRP." (PMID 40507489, 2025). "C-reactive protein (CRP) is an acute-phase protein that is synthesized by hepatocytes in response to inflammatory stimuli and can be increased in various conditions, such as infections, trauma, autoimmune diseases, or malignancies." (PMID 40141426, 2025). "CRP is a non-specific inflammatory marker widely used in various diseases such as cardiovascular disease, autoimmune diseases, and infectious diseases." (PMID 39820962, 2025). "Thus, in autoimmune diseases, such as systemic lupus erythematosus (SLE), severe systemic inflammation is common, and inflammatory markers such as ESR and CRP can reach significantly elevated values." (PMID 40427060, 2025). "There was no clear difference in baseline CRP levels between patients with and without autoimmune diseases or glomerulonephritis or vasculitis." (PMID 38530490, 2024). "CRP, is another APR, mainly produced in the liver, widely used as a biomarker in inflammatory diseases, that increases mostly in response to microbial components during infections and in autoimmune diseases." (PMID 38953032, 2024). "H3Cit-DNA, but not cfDNA, NE or CRP, was significantly elevated in patients with cancer compared to patients with autoimmune disease (p = 0.0001)." (PMID 38941006, 2024). "Nevertheless, confronted by the challenge of lack of specificity being incorporated in a vast spectrum of chronic infections and autoimmune diseases, CRP has not been affirmed as a potent conclusive marker in this regard." (PMID 39039277, 2024). "Additionally, CRP can be elevated due to many factors unrelated to IBD, including infection and rheumatoid and autoimmune diseases." (PMID 37751311, 2024). "In the HDD-CKD study, there was no clear difference in baseline CRP levels between patients with and without autoimmune diseases or glomerulonephritis or vasculitis." (PMID 38530490, 2024). "GA, PROM, maternal autoimmune diseases, and cesarean delivery were all independent influences on neonatal CRP ≥ 8 mg/L on admission, and there was a nonlinear relationship between GA and neonatal CRP ≥ 8 mg/L on admission." (PMID 38302903, 2024). "Both ESR and CRP are non-specific markers of inflammation, being increased in malignancy, infection and autoimmune disease." (PMID 38505536, 2023). "Recently, results from a large-scale RCT study (n = 25.871) on vitamin D supplementation found a decreased incidence of autoimmune diseases and indications of reduced CRP after 2 but not 4 years." (PMID 37550771, 2023).
autoimmune disease (continued). "Second, potential confounding factors affecting serum albumin and CRP levels, such as infections and autoimmune diseases, were not assessed." (PMID 37816855, 2023). "CRP is greatly influenced by non-infectious factors such as cardiovascular disease and autoimmune disease." (PMID 37698429, 2023). "However, it is believed that autoimmune diseases where the type I interferon gene signature predominates, such as SLE, deviate from the usual pattern where CRP levels typically correlate with the degree of inflammation." (PMID 37762312, 2023). "Curcumin and Curcuma longa Extract may regulate inflammatory cells (such as Treg) and inflammatory factors (such as CRP, ESR, TNF-α, TGF-β1, IL-6 level), which may be its mechanism for treating autoimmune diseases." (PMID 35979355, 2022). "Laboratory tests revealed normal white blood cell count, C-reactive protein, and angiotensin-converting enzyme and negative blood culture and antibodies for autoimmune diseases." (PMID 34498198, 2022). "Normal levels of antinuclear antibodies, rheumatoid factor, CRP, and ESR could exclude autoimmune diseases, especially JIA." (PMID 36050454, 2022). "During inflammation and infection both CRP expression and PMN activation level are upregulated, which might explain sudden relapses or exacerbations of antibody-mediated autoimmune diseases following infection." (PMID 33790888, 2021). "Laboratory examination of this disease may reveal elevated CRP and AESR at disease onset as well as the presence of autoantibodies to varying degrees, thus patients may present with characteristics of autoimmune disease." (PMID 34030699, 2021). "In this regard, all T cell mediated autoimmune diseases like SLE and RA could theoretically be improved by CRP with the help of APCs." (PMID 33841391, 2021). "Correlation analysis showed that serum concentration of HMGB1 was moderately correlated with CRP in infectious diseases subgroup, and the serum concentration of anti-HMGB1 antibodies was strongly correlated with erythrocyte sedimentation rate in autoimmune disease subgroup." (PMID 33658546, 2021). "The combined test CRP and PV gave an increase of 0.022 in the AUC for autoimmune disease, which was statistically significant, but seems unlikely to be clinically significant." (PMID 31208975, 2019). "The authors did not compare the accuracy of CRP versus PV for subtypes of autoimmune disease due to the smaller sample size for PV tests." (PMID 31208975, 2019). "Zhang and co-workers also found higher levels of CRP in NMOSD patients with autoimmune diseases than in those without autoimmune diseases." (PMID 30355349, 2018). "Specifically, nationally scaled studies have demonstrated increased autoimmune disease frequency in the parents of children with ASD, increased gestational C-reactive protein in mothers of children with ASD, and increased frequency of ASD after pregnancies complicated by infection." (PMID 27842596, 2016). "In most of the autoimmune diseases without systemic infection, the serum PCT levels are within normal range (<0.05ng/ml) but CRP can be elevated in patients with active underline disease." (PMID 26182343, 2015). "The effect of marine-derived n-3 PUFAs from dietary intake was only assessed in subjects with chronic non-autoimmune disease, and a significant lowering effect was observed on IL-6, but not on CRP and TNF-α." (PMID 24505395, 2014). "Serum C-reactive protein (CRP) was significantly lower in NMOSD patients without autoimmune diseases than NMOSD patients with autoimmune diseases (p = 0.017)." (PMID 25135481, 2014). "In comparison with non-autoimmune conditions, patients with autoimmune disease had higher IgG levels, lower white blood cell counts, lower hemoglobin values, and lower C-reactive protein (CRP) levels." (PMID 24180594, 2013). "CRP is characteristically high in early and flaring RA, but not in other autoimmune diseases (e.g., systemic lupus erythematous, scleroderma, and PsA)." (PMID 24192039, 2013).
autoimmune disease (continued). "In our study, NZB/W mice were injected with chromatin, which accelerates their autoimmune disease, in the presence or absence of CRP." (PMID 24167754, 2013). "Although a fairly non-specific biomarker, the circulating concentration of CRP rises rapidly (within hours) in response to most forms of tissue damage, infection, and other acute inflammatory events including autoimmune diseases and malignancy." (PMID 18445267, 2008). "Furthermore, clinical data on other ratios like the aspartate transaminase (AST)-to-alanine transaminase (ALT) ratio, ESR/CRP ratio, and CRP/albumin ratio, which have been analyzed in autoimmune diseases, are still lacking in SSc to the best of our knowledge." (PMID 41464713, 2025). "However, CRP is nonspecific and can be elevated in various diseases, including chronic infections and autoimmune disorders often seen with CSU, though levels are generally lower in CSU." (PMID 39483682, 2024). "Plasma CRP is a sensitive yet non-specific biomarker of systemic inflammation and induced under various conditions including infection, trauma and other inflammatory states such as autoimmune disease." (PMID 37982862, 2024). "Additionally, integrating GFAP into biomarker panels with CRP, IL-6, and ANCA could improve diagnosis and treatment monitoring in autoimmune diseases." (PMID 39459426, 2024). "However, CRP is not specific to MS and can be elevated in a variety of other conditions such as infections, autoimmune diseases, and even physical trauma." (PMID 39202006, 2024). "CRP, erythrocyte sedimentation rate (ESR), anti-neutrophil cytoplasm antibodies (ANCA), anti-saccharomyces cerevisiae antibodies (ASCA), Leucine-Rich α2 Glycoprotein, and fecal calprotectin are commonly-used biomarkers as indicators of disease activity in patients with autoimmune diseases like IBD." (PMID 38486190, 2024). "GA, PROM, maternal autoimmune diseases and cesarean delivery were all independent influences neonatal CRP ≥ 8 mg/L on admission, and there was a nonlinear relationship between GA and neonatal CRP ≥ 8 mg/L on admission." (PMID 38302903, 2024). "The incidence of TRAEs was significantly higher in elderly patients (≥ 65 vs < 65 years; ≥ 75 vs < 75 years); patients with lower C-reactive protein levels (< 5 vs ≥ 5 mg/dL); and patients with vs without a past medical history, including hepatic, thyroid, and autoimmune diseases." (PMID 35441907, 2022). "However, many non-infectious conditions such as allergies and autoimmune diseases can dramatically influence CRP and ESR values, whereas PCT does not change significantly in some Gram-positive bacterial and fungal infections or local infections." (PMID 36760236, 2022). "In addition, stress and autoimmune diseases were not taken into account although they have an influence on CRP." (PMID 32082531, 2019). "Also, CRP has a role in autoimmune diseases as it can bind to auto-antigens; thus, immune-mediated conditions like GBS can stimulate inflammatory response which in turn lead to in an increase in CRP level." (PMID 29780224, 2018). "Other studies suggest that increased IL-33 levels correlate with the acute-phase inflammatory response in autoimmune diseases such as systemic lupus erythematosus where the levels of serum IL-33 are positively correlated with the erythrocyte sedimentation rate (ESR) and C reactive protein (CRP)." (PMID 30034292, 2018). "However, the clinical usefulness of CRP as a cancer biomarker is limited by its nonspecific elevation due to noncancer‐related conditions including infection, autoimmune disease, and cardiovascular disease." (PMID 27350148, 2016). "This may be explained by the non-specificity of CRP as a rapid inflammation marker; it increases in response to various conditions including infection, cardiovascular disease, and autoimmune disease as well as tumor progression." (PMID 25612215, 2015).